CD4 (CD4 molecule)
Diseases named in the same sentence as CD4 in open-access papers (continued):
Sharing a sentence is not in itself a finding about the gene and the disease.
tumor (continued). "The micrometastatic niche, for example, is rich in platelet and tumor-cell-derived TGF-β, which suppresses both CD4+ and CD8+ T-cell activity." (PMID 37298230, 2023). "In C57BL6/J mouse models with CT-2A glioblastoma, the Zika virus has been shown to promote intratumor infiltration of CD4+ and CD8+, thereby altering the tumor microenvironment and promoting antitumor action." (PMID 37896752, 2023). "Moreover, CD4+ T cells can also modulate other subsets to indirectly improve antitumor and antichronic viral responses, such as the interaction of CD4+ T cells with B cells, the regulation of macrophage polarization, and the modulation of vessel system formation in tumor tissue." (PMID 37829505, 2023). "The tumor microenvironment is infiltrated with a variety of immune cells, mainly B cells, CD8+ T cells, CD4+ T cells, dendritic cells, macrophages, and neutrophils." (PMID 35646925, 2022). "We demonstrated maximum priming of T cells in the tumor tissue with CD8+ T cells (9.5 ± 3.2%) and CD4+ T cells (18.4 ± 7.6%) suggesting local injection of R848 embedded in a smart nanosystem increases cytotoxic activities of T cells." (PMID 37693071, 2022). "CD4+ resident memory cells were predominantly found in the ascites, whereas CD8+ resident memory cells were only present in the primary tumor." (PMID 36077756, 2022). "GC-MSCs promote the activation of CD4+ T cells, which in turn, promote PD-L1 expression in GC-MSCs via p-STAT3 signaling, thereby promoting tumor growth." (PMID 36439438, 2022). "More specifically, CA patients had significantly greater numbers of CD4 and CD8 T cells, as well as increased vasculature within the tumor, indicating a more active immune response against tumor progression." (PMID 36923308, 2022). "Particularly noteworthy was that the expression level of the PD-1 receptor on the T CD4+ and T CD8 + lymphocytes from the tumor and lymph node samples increased with the N scale (more precisely, from N = 1 to N = 3)." (PMID 35158748, 2022). "The aim of the second part of the multicolor flow cytometric analysis was to evaluate the lymphoid cell subpopulation (CD4+, CD8+ T lymphocytes, NK cells, NKT cells), infiltrating the tumor tissue on the 3rd, 5th, and 7th days after vaccine administration." (PMID 35372586, 2022). "This M1 activation is characterized by an increase in p38/p65 signal transduction and proinflammatory cytokines, which promotes the infiltration and activation of CD4+ and CD8+ T cells in the tumor microenvironment." (PMID 37305350, 2022). "A study on EBV-related classic Hodgkin lymphoma showed many CD4+ and CD25+ regulatory T cells in tumor microenvironment." (PMID 35842661, 2022). "LAG-3 and PD-1 were highly co-expressed in CD4+T cells and CD8+T cells, and the inhibitory effect of the blocking of LAG-3 and PD-1 on tumor progression." (PMID 35874717, 2022). "CD4+ CD25+ Foxp3+ Tregs were the predominant immunosuppressive cells and conveyed the antitumour T cell effector functions in the subcutaneous CT26 tumour BALB/c mouse model used in this study." (PMID 35996405, 2022). "Reduction in the CD3+, CD4+, CD8+ and CD56+ T cell population in patients with advanced neoplasms reduces the lymphocyte-dependent antitumor cellular response which results in a worse prognosis." (PMID 35743468, 2022). "TIMER analysis also showed a negative correlation between G6PC expression and infiltration of immune cells within the tumor, such as infiltrating B cells, CD8+ T cells, CD4+ T cells, macrophages, neutrophils and dendritic cells." (PMID 35984176, 2022). "To determine how LAIT is globally affecting CD8+ and CD4+ T cell activation, we performed GSEA on total CD8+ or CD4+ T cells from the LAIT‐treated and CTRL tumours." (PMID 35808806, 2022). "Local delivery of this mRNA by intratumoral injection increased the CD4+ and CD8+ T cell populations in the spleen and tumor, promoting tumor immune infiltration and tumor suppression." (PMID 36313716, 2022).
tumor (continued). "In contrast to the direct tumor-killing effect of CD8+ T cells, CD4+ T cells play more of an immune-modulatory and paracrine role." (PMID 35844502, 2022). "While cluster 1 and 3 had a significantly higher abundance of resting memory CD4 T cells and decreased abundance of CD8 T cells as well as a lower immune score, therefore we assigned cluster 1 and 3 as a cold tumor." (PMID 35677557, 2022). "Favorable microbiota was also shown to promote the secretion of IL-12 by DCs to recruit, in the tumor beds, CCR9+CXCR3+CD4+ T cells." (PMID 35677057, 2022). "It is not hard to find that COL11A1 is closely related to the infiltration of various tumor immune cells including B Cell, CD8 + T cell, CD4 + T cell, macrophage and neutrophil and dendritic cell." (PMID 36160004, 2022). "Mice deficient in the Tnk2 gene encoding Ack1, are characterized by diminished CSK Y18-phosphorylation and spontaneous activation of CD8+ and CD4+ T cells, resulting in inhibited growth of transplanted ICB-resistant tumours." (PMID 36376335, 2022). "Anti-PD-1 antibodies in the tumor microenvironment activate CD8+ T cells, and CD4+ T cells mediate CD8+ T cell proliferation and dendritic cell maturation." (PMID 35053457, 2022). "Increased levels of antitumor TIICs, like CD4+T and CD8+T, were observed, whereas the levels of pro-tumor TIICs like Treg and Th2 were low in patients in the low-risk subgroup." (PMID 36518754, 2022). "For better understanding of the mechanism by which IM@ZP under NIR laser irradiation inhibits tumor growth, we further analyzed its effects on tumor infiltrating CD8 + and CD4 + T cells in vivo." (PMID 35236356, 2022). "Activated APCs then activate the immune cells, resulting in the generation of CD4+ T cells, CD8+ T cells, and NK cells directed toward tumor and viral antigens." (PMID 35860357, 2022). "Positive correlations were found between CD20 and Bcl2 (r=0.695, p=0.001), CD3 (r=0.598, p=0.550), CD4 (r=0.550, p=0.012), CD8 (r=0.567, p=0.009) and Ki67 (r=0.558, p=0.011), which confirm our previous findings in the tumor areas." (PMID 36685537, 2022). "Two effector CD4+ T cells, characterized by high expression of either IFNγ and TNF or GZMA and GZMK, showed an anti‐tumour function." (PMID 35184398, 2022). "Treatment with GC chemotherapy significantly decreased overall tumor-infiltrating CD3+ T cells, as well as CD4+ and CD8+ T-cell subsets when compared to vehicle-treated tumors (*P < 0.05, **P < 0.001)." (PMID 35347124, 2022). "While CD4+ T cells recognize neoepitopes shown by MHC II molecules, CD8+ T cells identify neoantigens in the context of MHC I molecules expressed by tumor cells, which triggers T-cell cytotoxicity and tumor cell killing." (PMID 35874694, 2022). "CD4+ Tregs and CD4+/CXCL13+ T cells were predominantly identified in tumour tissues, demonstrating that malignant cells are the key elements that induced immune‐tolerance." (PMID 36305631, 2022). "The vaccine conferred anti-tumor immunity and remodeled the tumor microenvironment (TME), resulting in increased infiltration of polyfunctional CD8+ and CD4+ T cells and reduced infiltration of immunosuppressive cell types within the TME." (PMID 36439126, 2022). "The evaluation of immune cell populations in 4T1 tumor-draining lymph nodes (TDLNs) showed a higher frequency of CD3+ and CD4+ cells while a lower frequency of suppressor cells such as Tregs and M-MDSC-LC." (PMID 36358804, 2022). "Based on the EPIC tool, we found CD4+ T cells, CD8+ T cells, and endothelial cells showed higher composition in tumor samples." (PMID 35692574, 2022). "A higher number of CD4+ and CD8+ T cells and a lower number of Treg cells post-thermal ablation have been shown to have a positive effect on tumor progression and survival." (PMID 36569954, 2022). "Patients in the high-risk group had a worse prognosis than those in the low-risk group, and they also had an abundance of infiltration of CD4+ T and CD8+ T cells to enhance the immune response to tumor cells." (PMID 35812755, 2022).
tumor (continued). "CD4+ and CD8+ T cells (absolute numbers of per mm2) within the tumor microenvironment were measured using a software based quantitative approach." (PMID 35158808, 2022). "DCs producing IL-18 and/or IL-12 also induced activation of CD4+ and CD8+ T cells in lymph nodes and high infiltration of CD4+ and CD8+ T cells to the tumor tissue." (PMID 35372586, 2022). "The total and proportion of tumor infiltrating CD8+ T cells and CD4+ T cells was significantly increased in small size of YCW NPs treated group, culminating with an inflamed tumor immune phenotype." (PMID 35013252, 2022). "Compared with controls, the infiltration of CD3+CD4+ T cells, CD3+CD8+ T cells, and NK cells was significantly increased in the tumor tissue and the percentage of G-MDSCs decreased to a certain extent." (PMID 36102418, 2022). "CD3 was chosen to analyze the levels of tumor-infiltrating T lymphocytes, while CD4 and CD8 stainings reflect the levels of tumor-infiltrating T helper cells and cytotoxic T lymphocytes, respectively." (PMID 36376922, 2022). "Further analysis on the relationship of LOX family members and tumor-infiltrating immune cells in LC found positive correlations between the infiltration of B cell, CD8+ T cells, CD4+ T cells, macrophages, neutrophils, and DCs and all LOX family members." (PMID 35311155, 2022). "Treg cells are a subset of CD4+ T cells that suppress innate and adaptive immune responses mainly by secreting IL-10 and TGF-β, which are known to promote tumor progression by inhibiting antitumor immune response." (PMID 35433771, 2022). "LAG-3 is expressed primarily on NK cells, B cells, CD4+, and CD8+ T cells, where it blocks T cell receptor signaling by binding with high affinity to MHC class II molecules, thereby decreasing anti-tumor T cell activity." (PMID 36106025, 2022). "The discovery that CD3+, CD4+, and CD8+ T cells were more sensitive to CAP treatment than tumor cells in this study is disconcerting." (PMID 35326381, 2022). "Future studies will further clarify this relationship between CD4+ FoxP3+ Tregs and cytotoxic CD8 T cells in the HNSCC tumor microenvironment following BRB-E administration." (PMID 36016924, 2022). "When tumor bearing mice were treated with Salmonella + Alb-IL2, we observed increased frequencies of intra-tumoral CD4 and CD8 T cells as well as elevated levels of pro-inflammatory cytokines (IFNγ, TNFα, IL-2) in the tumor associated CD8 T cells." (PMID 35962391, 2022). "Here, we used Ad-LVs to analyze the function of CD4+ and CD8+ CAR T cells in a hematological in vitro tumor model." (PMID 36298713, 2022). "They reported that ectonucleotidase-expressing CD25high Th17 cells dramatically increased in tumor tissue and exhibited suppressive function via inhibition and activation of CD8 and CD4 cells, respectively." (PMID 35248028, 2022). "Previously, we have measured immune cell infiltrates in these MB tumor tissues, including CD3+ T cells, CD4+ T cells, CD8+ T cells, CD20+ B cells, NK cells, FOXP3+ regulatory T cells, and γδT cells." (PMID 34988920, 2022). "KIAA1429 expression showed a weak positive correlation with LUAD tumor purity, CD8+ T cells, CD4+ T cells, macrophages, neutrophils, and dendritic cells and a weak negative correlation with B cells." (PMID 38089085, 2022). "Ex vivo, tumor infiltration by CD8+, NKp46+ and also CD4+/FoxP3+ immune cells correlated with a better outcome." (PMID 36268020, 2022). "Increases in terms of fold changes in CD4/CD8+ T cells and CD11c+ DCs in the lung metastatic sites were significantly higher than those in the primary tumor (CD8+ T cells: p = 0.019, CD4+ T cells: p = 0.004, CD11c+ DCs: p = 0.017)." (PMID 35052851, 2022). "In this profile, there are abundant CD4+ and CD8+ cells, effector T cells are near tumor cells, and there is an abundance of cytokines and proinflammatory markers." (PMID 35740462, 2022).
tumor (continued). "The infiltration abundances of Act CD4 and Tem CD8 in LUAD tumour tissue were negatively correlated with the expression of FOXP1, and FOXP1 was low in LUAD tissue." (PMID 36160018, 2022). "The immune-inflammatory type refers to the infiltration of CD4+T, CD8+T and other immune cells in the tumor parenchyma, which is related to the inflammatory response." (PMID 36532001, 2022). "Additional studies will support the dissection of the role of CD4+ and CD8+ CAR T cells in tumor lysis and persistence." (PMID 36298713, 2022). "More recently, a synthetic consensus sequence approach to provide MHC class II help was used to develop a FAP DNA vaccine, which was shown to synergize with other tumor antigen-specific DNA vaccines to enhance CD8+ and CD4+ antitumor immunity." (PMID 36338519, 2022). "Overall sharing of TCR clonotypes from neoantigen-specific peptide expanded cultures and tumor tissue was 12% (n=21 CD8 and n=15 CD4) and 14% (n=95 CD8 and n=40 CD4) for primary tumor and metastasis, respectively." (PMID 35361728, 2022). "L-Arg bacteria and PD-L1 blockers can synergistically inhibit tumor growth, increase the infiltration of CD4+ and CD8+ T cells, and reduce the infiltration of Treg cells in the tumor." (PMID 35898872, 2022). "A2AR blockade reduces CD4+ FOXP3+ Tregs infiltration and enhances the anti-tumor response of CD8+ T cells by attenuating hypoxic HIF-1α signaling." (PMID 36532071, 2022). "Exclusive pathways in CD4+ cells, CD8+ cells and Tregs, and common pathways for the tumor-infiltrating T-cell subsets were identified." (PMID 36232369, 2022). "All four mice injected with NA5-ECD8 cells developed CD8 + CD4- tumors with either CD3- cells or CD3+ cells, as observed in CD8+ ALCL tumor cells." (PMID 35246138, 2022). "On the other hand, CD4+ T cells have the ability to directly kill tumor cells by IFN- even in the absence of CD8+ T cells, indicating that CD4+ T cells are essential for tumor immunity." (PMID 36230580, 2022). "Tumor-specific CD4+ T cells can reject tumor cells better than CD8+ T cells, as well as collaborate with NK cells to eradicate tumor." (PMID 36005179, 2022). "Anti-PD-1 treatment moderately increased the tumor infiltration of CD45+CD8+ T cells and CD45+CD4+ T cells and decreased the infiltration of CD11b+Gr1+ myeloid cells and CD4+FOXP3+ Treg cells in shControl mice." (PMID 35265200, 2022). "Activated DCs process and present tumor antigens to the naïve CD4+ and CD8+ T cells which reside in the tumor draining lymph nodes." (PMID 35757015, 2022). "It was highly expressed in malignant tumors and promotes the infiltration of CD4+ and CD8+ lymphocytes into tumor cell regions to kill tumor cells." (PMID 35145917, 2022). "We assume that the inactive CD4+ and CD8+ T cells that migrated from the lymph nodes into the tumor microenvironment have constant densities T^1 and T^8, respectively, at the tumor boundary, and that they are activated by IL-12 upon entering the tumor." (PMID 35015785, 2022). "The results from this study have shown varying CD4/CD8 ratios across the TIL cultures and it would be interesting to see if the ratio in the primary tumour was conserved throughout the expansion process." (PMID 35158816, 2022). "CD4+ central memory precursor T cells (expressing CCR7, SELL, IL7R) were the most abundant subtype in tumor tissue, whereas the effector and effector memory T cells were abundant in the adjacent tissue." (PMID 35757757, 2022). "Experimental results have shown that TECs can induce immune responses of tumor antigen-specific CD8+ T cells through the PD-1/PD-L1 pathway and evade tumor immunity by regulating immunosuppressive CD4+ T cells in an antigen-specific manner." (PMID 35464435, 2022). "The densities of CD3+CD4+ cells (CD4+ T cells), CD3+CD8+ cells (CD8+ T cells), CD4+Foxp3+ cells (Treg cells), and CD204+ cells were compared with the patients’ background tumor characteristics." (PMID 35462552, 2022).
tumor (continued). "Our observation of increased frequency of Tregs with an activated phenotype combined with dysfunctional TIGIT‐expressing CD4 and CD8 T cells suggests dampening of anti‐tumor T‐cell responses in lymph nodes with established metastases." (PMID 34165864, 2022). "Multiparameter flow cytometry analysis of myeloid and lymphoid cells in tumors confirmed a high percentage of CD4+ and CD8+ T cells in the tumor tissue obtained from mice treated with DC/IL-18 + IL-12/TAg, 7 days after the administration of vaccines." (PMID 35372586, 2022). "The mature APC subsequently provides immunogenic information and produces tumor-specific killers (CD8+) and helper (CD4+) T-cells and activates antitumor T-cell immunity." (PMID 35681533, 2022). "In parallel with our study, the enhanced anti-tumor effect in combination treatment was mediated by the increased infiltration of CD45+ immune cells, CD4+ and CD8+ TILs in addition to decreased percentage of CD11b+ Ly6G+ cells." (PMID 36605208, 2022). "Despite a wide array of evidence supporting a predominant role of cDC1s in anti-tumor immunity, CD1c+ CD14− cDC2s also participate by infiltrating tumors and triggering CD4+ T cell responses at tumor draining lymph nodes." (PMID 36230990, 2022). "Analysis of the tumor immune infiltrate showed that DMXAA monotherapy up-regulated production of anti-tumor cytokines (i.e., IFNγ, Granzyme B, and TNFα) in both CD8+ and CD4+ T cells, which was further enhanced by combining with olaparib therapy." (PMID 35641483, 2022). "CD45+CD3+CD4+IL4+ T-cells were present in both FAK-wt and FAK−/− tumours at similar levels, and IL4 expression by these cells was also similar." (PMID 36138073, 2022). "The CXCL16 immunohistochemical analysis of 58 colorectal samples, collected during surgery, demonstrated a higher CD4 and CD8 tumor infiltration in patients who exhibited a high level of this chemokine expression." (PMID 36429101, 2022). "Researchers have found that exosomes in supernatant and serum of tumor cells from AML patients contain IL-10 and TGF-β1, and these exosomes promote CD4+CD25- T cells proliferation and transformation into CD4+CD25+Foxp3+T cells." (PMID 35692747, 2022). "Tumor-derived EVs induced apoptosis of CD8+ T cells and were also able to alter the differentiation of CD4+ T cells into a state that suppresses cytotoxic T cell activity, contributing to tumor escape from the immune system." (PMID 36354586, 2022). "Since CD4+-TIL depletion with anti-PD-1 treatment completely lost the efficacy in Hepa1-6, our results suggest the balance between TIL-CD4+-Teff and immuno-suppressive environment inclusive of G-MDSC playing critical roles of anti-PD-1 MOAs in this tumor." (PMID 35228603, 2022). "Cancer vaccinations are primarily employed to augment antigen-specific CD4+ and CD8+ T cells, which in turn help in the recognition and eradication of tumor cells." (PMID 36362963, 2022). "Another study also indicated that siRNA against PD-L1 or PD-L1 improved effector functions of tumor-specific CD4+ and CD8+ T cells in vitro, suggesting that PD-L1/PD-L2 siRNA is an exciting strategy to inhibit the immune suppressive tumor-specific T cells." (PMID 36003395, 2022). "An additional study in the RCC mice model demonstrated that high-dose Vit-C therapy alone led to tumor infiltration by both CD4+ and CD8+ T cells and elevated the ratio CD8+/CD4+, while regulating the production of numerous cytokines and chemokines." (PMID 35745630, 2022). "Potential reasons may include a decrease in monocyte engagement in the preinvasive tumor microenvironment (TME) causing a depletion in tumor-associated macrophages (TAMs); or explained by the relation between HPV and human immune system like cell immunity such as CD4/CD8 T cell." (PMID 36568201, 2022). "Studies have confirmed that certain types of TILs, such as CD4+ T and CD8+ T cells, can inhibit tumor growth and have immune effects on tumor patients." (PMID 36124030, 2022).